VDR (vitamin D receptor)
Diseases named in the same sentence as VDR in open-access papers (continued):
Sharing a sentence is not in itself a finding about the gene and the disease.
cancer (continued). "In conclusion, 1α,25(OH)2D3 radiosensitizes cancer cells that depend on VDR, by activating the NADPH oxidase complex, which further increases the ROS level and induces apoptosis." (PMID 32848720, 2020). "Based on the observations that inhibition of IRX4 decreased NANOG-mediated cancer cell stemness, we examined the relationship between 1,25(OH)2D3/VDR and IRX4-induced NANOG expression." (PMID 32820157, 2020). "Cytofluorimetric and protein analysis revealed that vitamin D-nanoemulsion causes a cell cycle arrest in G0/G1 phase in colorectal, breast and prostate cancer cells expressing VDR." (PMID 32560347, 2020). "In normal cancer cells and cancer stem cells, 1,25(OH)2D3 signaling starts upon binding with VDR and exerts its anticancer activities by either regulating target gene expression or through non-genomic regulations of different signaling pathways." (PMID 32679655, 2020). "VDR is expressed in most normal human cell types and tissues, but also in cancer cell lines and tumors of diverse origins." (PMID 33227961, 2020). "Accumulating evidence has suggested that lower circulating vitamin D levels are related to a higher incidence of developing various cancers, probably through the genomic effects regulated by VDR." (PMID 32285621, 2020). "This review aims to provide an up-to-date overview on the effects of vitamin D and its receptor (VDR) in regulating inflammation, different cell death modalities and cancer." (PMID 32679655, 2020). "Calcitriol was previously found to increase VDR expression in different cancer cells, as well as in bronchial epithelial cells and peritoneal mesothelial cells, along with inhibition of epithelial to mesenchymal transition." (PMID 33133014, 2020). "Compared with the non‐cancer tissues, VDR is abundantly expressed in the PTC tissues, which is generally concentrated in cytoplasm (45/80, 56.2%)." (PMID 32285621, 2020). "A well-characterized example of histone modification mediated by nuclear receptors is that 1α,25(OH)2D3, known as calcitriol or active form of vitamin D, can regulate histone modification and can inhibit cancer progression through the vitamin D receptor (VDR)." (PMID 32245092, 2020). "Many studies show that calcitriol is a promising co-adjuvant for the treatment of tumors expressing VDR; nevertheless, the use of vitamin D as an adjuvant in cancer therapy is a matter of discussion." (PMID 32210800, 2020). "Calcitriol is the active form of vitamin D with beneficial effects on anti‐cancer by binding vitamin D receptor (VDR)." (PMID 32285621, 2020). "Specifically, 1,25(OH)2D upregulated the androgen receptor and dihydrotestosterone inhibited the growth of cancer cells by upregulation of VDR." (PMID 32024052, 2020). "First, the analysis of tumor biopsies from 658 patients showed that high VDR expression in CAFs is associated with better patient overall and progression-free survival, independently of the level of VDR expression in carcinoma cells." (PMID 32854355, 2020). "The active vitamin D metabolite 1,25(OH)2D3 and other synthetic VDR agonists are differentiation agents that enforce an epithelial state in carcinoma cells largely through the induction of key epithelial proteins and the inhibition of EMT." (PMID 32854355, 2020). "Despite promising results from preclinical studies, most clinical trials that employed vitamin D for cancer therapy and prevention have yielded underwhelming results, which reflects an inadequate understanding of VDR actions in both tumor and stromal cells." (PMID 30925918, 2019). "Based on findings derived mostly from cell culture studies and a few in vivo animal cancer models, the functions of VDR, PPARs, AR, ER and GR in tumor-supporting cells are relatively well-characterized." (PMID 30925918, 2019).
cancer (continued). "Epidemiological and experimental studies reveal that the VDR and its ligands are promising targets for the prevention and possible treatment of cancer, autoimmune diseases, and infections, as well as of bone and mineral disorders." (PMID 31534963, 2019). "VDR is widely expressed in most cell types, but the expression is progressively reduced during dedifferentiation and tumor progression in many cancer types." (PMID 29657326, 2018). "As expected, both SPP1 and CYP24A1 were more induced in CSCs compared to their corresponding bulk cancer cells by the same dose of calcitriol, indicating that CSCs are more sensitive to low dose calcitriol in the activation of the VDR pathway signaling." (PMID 29581858, 2018). "We then treated 2008 and Kuramochi CSCs and their corresponding bulk cancer cells with calcitriol, and analyzed expression of two VDR downstream genes SPP1 and CYP24A1, which possess vitamin D-responsive element." (PMID 29581858, 2018). "RXRB is a member of the retinoid X receptor (RXR) families mediating the effects of retinoic acid, and the mutual heterodimers with vitamin D receptor (VDR) are involved in cancer developments." (PMID 29515775, 2018). "The experimental trials performed in animal models provided evidence that VDR agonists have a therapeutic potential in chronic inflammatory diseases and cancer." (PMID 30011902, 2018). "Because we confirmed our observations in different models of both normal and cancer cells, we conclude that VDR is essential for the health of human tissues." (PMID 29874855, 2018). "In cancer cells, 1,25(OH)2D/VDR activates cyclin-dependent kinase inhibitors (e.g., p21, p27), inhibits mitogenic growth factors such IGF-1 and EGF, and promotes the activity of TGF-β, thus inhibiting cell proliferation and cancer growth." (PMID 29951549, 2018). "VDR mediate the biological activity of vitamin D and plays a crucial role in the etiology and development of cancer." (PMID 29560132, 2018). "Vitamin D has roles in proliferation, apoptosis, and cell adhesion in cancer tissues showing its effects through the VDR." (PMID 29391329, 2018). "VDR-stromal reprogramming weakens the capacity of the PSCs to support cancer growth via stromal remodeling, alters the PSC phenotype to a more quiescent nature, and ultimately reduces fibrotic content and increases tumor vasculature." (PMID 30400571, 2018). "Based on the cancer cell line controls, we classified two VDR staining statuses for the CTCs: positive if low, moderate, or high expression; or negative." (PMID 28632174, 2017). "VDR localization and its specific effects are an emerging field of research and the findings we reported in this study contribute to our understanding of the phenotypic effects of cytoplasmic VDR on cancer cells." (PMID 28460457, 2017). "In conclusion, the present study suggests that VDR overexpression in animal models of cancer cachexia is likely contributing to skeletal muscle wasting through an impairment of the muscle regenerative program." (PMID 28423519, 2017). "VDR expression is reported in many cancers types including breast, prostrate, pancreas, colon, leukaemia’s and lymphomas." (PMID 28963501, 2017). "As the key component of the vitamin D metabolism process, VDR similarly participates in the regulation of cancer development." (PMID 28489590, 2017). "Well established ligand-mediated nuclear actions of the VDR include inhibition of cancer cell proliferation, induction of apoptosis, and inhibition of metastasis by regulating cell migration and invasion." (PMID 28460457, 2017).
cancer (continued). "This novel ligand-independent function of the VDR to promote cancer cell growth contrasts with its canonical ligand-dependent inhibitory nuclear actions on cell growth in the presence of vitamin D." (PMID 28460457, 2017). "In contrast, MDA-VDR-KD cells demonstrated no significant change in CYP24 expression, confirming efficient abrogation of VDR signaling in these cancer cells." (PMID 28944088, 2017). "Mechanistically, we established that knockdown of the VDR in cancer cells interferes with the Wnt/β-catenin signaling pathway." (PMID 28944088, 2017). "In conclusion, the current study demonstrates that the unliganded VDR possesses intrinsic functions that control cancer cell growth in a ligand-independent manner through interference with the Wnt/β-catenin signaling pathway." (PMID 28944088, 2017). "VDR functions have a broad impact, contributing to cancer development once it regulates cell proliferation and cell cycle control." (PMID 27066374, 2016). "The detection of Vitamin D Receptor (VDR) gene polymorphisms may be useful as a molecular indicator of clinical outcome, once VDR is implicated in a wide variety of biological processes including modulation of the immune response and inhibition of cancer cell growth, angiogenesis and metastasis." (PMID 27066374, 2016). "VDR agonists play a pivotal role in the regulation of pre-mRNA splicing and microRNA (miRNA) processing in cancer cells." (PMID 27973439, 2016). "It is well established that inhibition of proliferation and stimulation of differentiation of various cancer cell lines by vitamin D and its analogs requires the expression and activity of VDR." (PMID 26760999, 2016). "VDR protein is expressed in almost all normal human cell types and tissues, and also in cancer cell lines and tumors of several origins." (PMID 26880977, 2016). "VDR signaling is activated upon binding of vitamin D and plays a role in cancer progression as well as cross-talks with multiple other pathways." (PMID 27092172, 2016). "Support for an anti-death function of the VDR comes from the observation that stable transfection of cancer cells with VDR confers resistance against arsenite-induced cell death." (PMID 26950144, 2016). "These lines of evidence prompted us to study the mechanisms responsible for VDR downregulation in cancer." (PMID 26880977, 2016). "It has shown that the VD/VDR is epigenetically downregulated in late cancer stages but overexpressed or normally expressed in early stages." (PMID 27579030, 2016). "More than sixty SNPs of the VDR gene located in the promoter region have been discovered in relation to cancer occurrence and prognosis." (PMID 27309378, 2016). "The idea that the VDR gene may influence the occurrence of PCa and other diseases is mainly based on the notion that vitamin D is implicated in a wide variety of biological processes including modulation of the immune response and inhibition of cancer cell growth, angiogenesis and metastasis." (PMID 27066374, 2016). "1,25D elicits its antiproliferative effects on cancer cells through binding to the ligand-activated transcription factor, VDR." (PMID 26909599, 2016). "Involvement of VDR in multiple pathways and points of convergence within these pathways indicate its possible importance for etiology of cancers." (PMID 26179909, 2015). "Both healthy and cancer breast cells express the VDR and gene ablation studies have shown a role of VDR in physiological mammary gland development." (PMID 26000308, 2015). "The vitamin D receptor (VDR) is a ligand-dependent transcription factor that regulates a wide range of cellular processes central to cancer development, including apoptosis, cell proliferation, differentiation, angiogenesis, and metastasis." (PMID 28480224, 2015). "In cancer pathogenesis, the activated VDR is suggested to act antiproliferatively and to regulate cell differentiation and apoptosis." (PMID 26699871, 2015).
cancer (continued). "We observed significantly higher levels of both p63 and VDR expression in NMSCs when compared with normal skin indicating a possible correlation between p63 and VDR in these cancers." (PMID 26068789, 2015). "VDR expression was lowest in more advanced (pT2b–pT4) (p = 0.005 with Mann–Whitney U test) and metastasizing cancers (p < 0.05 and p = 0.004 with Mann–Whitney U test for nuclear and cytoplasmic VDR immunostaining, respectively)." (PMID 26501255, 2015). "1, 25-dihydroxyvitamin D3 (calcitriol) acts through the vitamin D receptor (VDR) as a modulator of the immune system, cancer cell proliferation, and apoptosis." (PMID 26075205, 2015). "Given the role of p63 and VDR in the inhibition of cell invasion, it came as a surprise that both VDR and p63 show high expression in the more invasive cancer, SCC, when compared with the precursor of SCC." (PMID 26068789, 2015). "Vitamin D3 is a secoster oid that exerts its effect by binding to its nuclear receptor called vitamin D receptor (VDR), inducing apoptosis and thereby inhibiting cell proliferation in cancer cells." (PMID 25799416, 2015). "VDR/β-actin protein levels, measured in the entire series of tumor specimens, showed results similar to VDR mRNA in terms of difference between benign and malignant tumors (0.20 ± 0.2 versus 0.04 ± 0.06 arbitrary units, P < 0.05)." (PMID 26843863, 2015). "In the present study, a significant reduction in VDR level was found in cancers with wider extension of NDs." (PMID 26501255, 2015). "With respect to cancer, studies using animal models have shown that knocking out VDR induces many types of cancers, including mammary, prostate, and colon cancers." (PMID 26075246, 2015). "The role of VDR in various cellular pathways suggests it plays a crucial role in the etiology and development of cancer." (PMID 25195132, 2014). "We propose that the VDR acts as a mitochondria-targeting tumor facilitator, the signaling of which supports cancer cell metabolism through the suppression of mitochondrial respiration and rewiring of metabolic intermediates toward biosynthesis." (PMID 25546457, 2014). "Polymorphisms of genes encoding components of the vitamin D pathway including vitamin D receptor (VDR) and vitamin D binding protein (DBP) have been widely investigated because of the complex role played by vitamin D in cancer tumorogenesis." (PMID 25541958, 2014). "Patients with high levels of SNAIL1 and SNAIL2 can be expected to have lower VDR expression and, therefore, will be poor responders to anti-cancer therapy with 1,25(OH)2D3 or its analogs." (PMID 25522365, 2014). "Having detected the widespread mitochondrial expression of the VDR, we sought to confirm that VDR ablation compromises cellular proliferation; thus, we abolished VDR expression in all of the cancer cell lines using genetic silencing." (PMID 25546457, 2014). "Consistent with this concept, some data suggests that phytoestrogens such as resveratrol and genestein can alter VDR expression and 1,25(OH)2D3 sensitivity in cancer cells in vitro." (PMID 24982636, 2014). "In the present study, we demonstrated that the VDR promotes proliferation, as its silencing strongly affects the growth rate of HaCaT and other cancer cell lines expressing a mitochondrial VDR." (PMID 25546457, 2014). "The histone deacetylase HDAC3, one of the most frequently upregulated genes in cancer, seems to inhibit VDR expression." (PMID 24808866, 2014). "We validated the general role of the VDR as an enhancer of cellular proliferation extending our observations to several human cancer cell lines." (PMID 25546457, 2014). "The VDR axis is reported to play a fundamental role with possible association between CRP and VDR gene polymorphisms, in cancer patients with cachexia." (PMID 24782788, 2014).
cancer (continued). "The signaling pathways of the VDR and the PPARs are interconnected in a large number of cancer cell lines." (PMID 24202445, 2013). "1,25-Dihydroxyvitamin D3 (1,25(OH)2D3), the active metabolite of vitamin D, exerts anti-cancer activities by binding to the vitamin D receptor (VDR) and modulating gene expression." (PMID 24217116, 2013). "Within 60 days of exposure, 88% of VDR null mice exposed to the chemical carcinogen DMBA developed cancer." (PMID 24086705, 2013). "VDR regulates a wide range of cellular mechanisms central to cancer development, such as apoptosis, cell proliferation, differentiation, angiogenesis, and metastasis." (PMID 23533810, 2013). "In five independently-derived primary cultures of cancer-associated fibroblasts, CYP24A1 expression was consistently induced in response to 1,25(OH)2D3 0.5nM indicating active VDR signaling in the tumor stroma." (PMID 23497279, 2013). "This review summarizes the roles of the PPARs and the VDR in pathogenesis and progression of cancer." (PMID 24202445, 2013). "In various cell types, including normal and cancer cells, the effects of aVitD and VDR mediated genomic pathways include the regulation of cell growth and differentiation." (PMID 24202445, 2013). "A variety of ligands influencing the PPARs and VDR signaling pathways have been shown to reveal chemopreventive potential by mediating tumor suppressive activities in human cancers." (PMID 24202445, 2013). "Further studies have to show if PPARs and VDR open new perspectives as agents inhibiting malignant potential of cancer." (PMID 24202445, 2013). "Ligands and other agents influencing the PPAR and VDR signaling pathways have been shown to reveal chemopreventive potential by mediating tumor suppressive activities in a variety of human cancers." (PMID 24202445, 2013). "Interaction of the PPARs and VDR signaling pathways has been shown at the level of molecular cross-regulation of their transcription factor in pathogenesis and progression of cancer." (PMID 24202445, 2013). "A relation between vitamin D and cancer is plausible as VDR, which is a nuclear receptor, is found in cells in a number of tissues and the active form of vitamin D, 1,25-dihydroxyvitamin D (1,25(OH)2D), appears to have anti-proliferative effects." (PMID 22649517, 2012). "Disturbances in CaR and VDR gene methylation patterns have been shown in tissues with rapid growth, such as in various cancer tissues, where these epigenetic changes were responsible for the uncontrolled cell growth." (PMID 23094155, 2012). "VDR has been demonstrated in a broad range of tumors and malignant cell types, and the inhibition of cancer cell growth, angiogenesis, and metastasis by calcitriol has been shown." (PMID 23094155, 2012). "To date, there is strong pre-clinical and clinical evidence to use the VDR as target for cancer therapy, since calcitriol has shown significant antineoplastic effects in vivo and in vitro." (PMID 22984610, 2012). "The application of calcitriol/vitamin D3 has emerged as an important strategy to target the vitamin D receptor (VDR) for cancer treatment." (PMID 21781307, 2011). "Since expression and functions of VDR, related vitamin D metabolic enzymes and vitamin D signal downstream genes are associated with vitamin D's action, genetic variation such as the single nucleotide polymorphisms (SNP) in these genes may have impact on vitamin D action in cancer cells." (PMID 21991434, 2011). "In cancer cells, numerous genes regulated by the VDR have been identified by expression microarrays." (PMID 20808524, 2010).